ABCB1 (ATP binding cassette subfamily B member 1)
Diseases named in the same sentence as ABCB1 in open-access papers (continued):
Sharing a sentence is not in itself a finding about the gene and the disease.
breast carcinoma (continued). "Germ line DNA samples from 230 patients with breast cancer on AC therapy were genotyped for the following SNPs: ABCB1 C1236T, G2677T/A and C3435T, SLC22A16 A146G, T312C, T755C and T1226C, CYP2B6*2, *8, *9, *3, *4 and *5, CYP2C9*2 and *3, CYP3A5*3 and CYP2C19*2." (PMID 20179710, 2010). "The FOXC1 methylation status might be a widely applicable prognostic factor for breast cancer patients while the methylation status of ABCB1 and GSTP1 might be a predictive factor for doxorubicin and perhaps anthracycline treatment in general." (PMID 20338046, 2010). "Interestingly, CyR‐SS‐L was more efficacious in inhibiting the proliferation of paclitaxel‐resistant breast cancer tumors than ICG by inhibition of ABCB1 and activating the mitochondrial apoptosis pathway with very little toxicity in normal cells due to the intelligent selectivity of PDT." (PMID 38898730, 2024). "Furthermore, GW2974 reversed ABCG2-and ABCB1-mediated drug resistance in breast cancer cell lines." (PMID 40836976, 2024). "Other biomarkers have also been hypothesized to influence outcomes, such as the anti-apoptotic marker bcl-2 and expression of the MDR1/ABCB1 drug efflux pump, for which upregulation has been associated with resistance to T-DM1 and other therapeutics in breast cancer." (PMID 36631725, 2023). "However, there is no consistency in the possibility of using ABCB1 polymorphisms as reliable breast cancer risk associated factors or chemotherapy response predictors." (PMID 35627114, 2022). "Moreover, ABCB1 was reported to limit the intracellular retention of the photosensitising agent benzoporphyrin derivative (BPD) in photodynamic therapy (PDT) in the MCF7 breast cancer cell line." (PMID 33801148, 2021). "Furthermore, recent findings in drug resistant ovarian and breast cancers showed evidence of multiple aberrant transcriptional fusions of ABCB1, placing it under control of alternative promoter regions from genes in chromosomal proximity to ABCB1." (PMID 35582031, 2021). "However, four out of six studies have found ABCB1 promoter hypermethylation in breast cancer." (PMID 33066132, 2020). "Also in breast cancer, miR-381 overcomes cisplatin resistance by targeting ABCB1." (PMID 35582590, 2019). "Furthermore, RNA samples from tumors extracted by surgery from 64 paired patients significantly increased PYGO2 and/or ABCB1 expression after chemotherapy, thus underlining a crucial role for the WNT/β-catenin pathway mediated by PYGO2 in the clinical chemoresistance of breast cancer." (PMID 31921125, 2019). "However, in a recent large genome-wide association study with over 100,000 unselected breast cancer cases this SNP and the ABCB1 gene were not among those identified as independently relevant for breast cancer risk." (PMID 30370250, 2018). "Specifically, ABCA1 (a major transporter of lipids out of cells), ABCB1, and BCRP are key players in breast cancer chemoresistance, and ABCB1 and ABCC1 are important indicators of breast cancer prognosis." (PMID 40869256, 2025). "To further validate the role of melatonin in reversing ABCB1‐mediated MDR, we also evaluated its effects on doxorubicin‐resistant MCF‐7 breast cancer cells." (PMID 41189280, 2025). "In order to study the relationship between ABCB1 (MDR1) and JUN expressions in breast cancer clinical samples, we analyzed TCGA transcriptomic databases." (PMID 39470848, 2025). "In this study, we explored the potential of siRNA-based therapies in combination with the chemotherapeutic agent vinorelbine to combat drug resistance in breast cancer cells, particularly MCF-7/ADR cells with high ABCB1 expression levels." (PMID 39206391, 2024). "The adriamycin (ADM)-selected breast cancer MCF-7/ADM cell line exhibited higher levels of ABCB1 and Y-box binding protein-1 (YB-1), and transfection of miR-137 reduced both YB-1 and ABCB1 levels." (PMID 39114355, 2024).
breast carcinoma (continued). "Deregulation of miR-451 was revealed in the DOX-resistant, human breast cancer cell line MCF-7/DOX, in which overexpression of ABCB1 contributes to DOX resistance." (PMID 39114355, 2024). "In breast cancer, TSN has the leverage to counter adriamycin resistance in vitro and in vivo via inhibition of the PI2K/Akt signaling pathway and downregulation of ABCB1." (PMID 37190065, 2023). "We aimed to determine the link between ABCB1 rs1045642, ABCC1 rs4148350, and ABCC1 rs3743527 and cardiotoxicity in breast cancer." (PMID 37367397, 2023). "The proliferation potential of breast cancer was inhibited after A1BG-AS1 knockdown, which was rescued by ABCB1 upregulation." (PMID 38007504, 2023). "Data obtained from the TCGA database also showed a statistically significant lowered average expression level of the ABCB1, ABCC4, ABCC6, and ABCG2 genes in patients with breast cancer compared to the control group." (PMID 36674773, 2023). "Among the delivered proteins are frequently described ATP-binding cassette (ABC) family, like P-glycoprotein (P-gp, MDR1, and ABCB1), breast cancer (BC)-resistant proteins (ABCG2, BRCP, and ABCA3), and multidrug-resistant protein 1 (MRP-1)." (PMID 36091133, 2022). "Intracellular drug concentration is controlled by ATP-binding cassette (ABC) transporters such as P-glycoprotein (ABCB1) and a breast cancer-resistant protein (ABCG2)." (PMID 35884363, 2022). "In contrast, long (12-days) exposure to talazoparib has been found to upregulate ABCB1, ABCC1, and ABCG2 mRNAs in another breast cancer model, MCF-10A." (PMID 36430819, 2022). "In a recent study, breast cancer cell lines MCF-7 and MDA-MB-231 showed increased copy numbers of ABCB1, ABCB4 (MCF-7 model), and ABCA9 (MDA-MB-231 model) to be associated with the formation of docetaxel resistance." (PMID 35631534, 2022). "P-gp/ABCB1 was the first ABC transporter discovered by Juliano and Ling in 1976 and was identified as overexpressed in breast cancer cells and responsible for MDR." (PMID 34959321, 2021). "ABCB1 was also found to render eribulin and cisplatin resistance in MCF7 and MDA-MB-231 breast cancer cells." (PMID 33801148, 2021). "ABCB1 protein was significantly overexpressed in paclitaxel-resistant SKBR3 and MCF7 breast cancer cells." (PMID 33801148, 2021). "Pimozide sensitizes breast cancer cells to DOX by suppressing the activation of STAT5a and downregulating ABCB1." (PMID 34336684, 2021). "Extracellular vesicles isolated from doxorubicin-resistant breast cancer cells carry high levels of UCH-L1 and ABCB1." (PMID 33920605, 2021). "With the presence of numerous binding sites, ABCB1 and ABCC1 can bind to and pump out a variety of chemotherapeutic drugs, such as Dox in breast cancer; paclitaxel and olaparib in ovarian cancer; and imatinib in chronic myelogenous leukemia." (PMID 34208283, 2021). "On the mRNA level, the efflux transporters ABCB1, ABCC1, and ABCG2 were found expressed in human heart, in normal and tumorous breast tissue, and in human breast cancer cell lines MCF-7, MDA-MB-231, and ZR-75-1." (PMID 35008681, 2021). "Miletti-Gonzalez and Chen found that interference with the expression or function of ABCB1 influences the motility and invasion of MCF7/AdrR breast cancer cells through interactions with CD44s." (PMID 33801148, 2021). "There is also evidence that GCS overexpression in breast cancer leads to AKT activation (p-AKT), which induces ABCB1 expression." (PMID 35004331, 2021). "ABCB1 was identified as a common mechanism of resistance to the CDK7 inhibitors, ICEC0942 and THZ1, in MCF7 breast cancer cells." (PMID 33801148, 2021). "Topotecan selected drug resistance was found related to expression and efflux activity of ABCG2 expression in human breast cancer cells or overexpression of both ABCG2 and ABCB1 transporters in human ovarian cancer cells." (PMID 33425914, 2020).
breast carcinoma (continued). "First, we evaluated the ALDH activity, the expression of BCSC genes (Nanog, Sox2 and Oct4), multiresistance pumps (ABCG2, ABCC1 and ABCB1) and the BCSC frequency (CD44+CD24+CD49+EPCAM+) in three human breast cancer cell lines." (PMID 33184339, 2020). "Recently, ABCB1 has been found to be upregulated through fusion of ABCB1 with SLC25A40, the gene upstream of ABCB1, in drug resistant high-grade serous ovarian and breast cancer." (PMID 33066132, 2020). "Prolonged in vitro daunorubicin exposure induced activating ABCB1 promoter translocations in human THP-1 AML cells, similar to those recently described in recurrent high-grade serous ovarian and breast cancers." (PMID 33167906, 2020). "Promoter methylation of ABCB1, ABCC1, and ABCG2 has been investigated in tumor, tumor-adjacent, and tumor-distant tissues from 16 breast cancer patients and normal breast tissues from four healthy women." (PMID 33066132, 2020). "Four human cancer cell lines, DLD-1 (colon cancer), SNB-75 (glioblastoma), Hs 578 T (breast cancer), and MDA MB 231 (breast cancer) were treated with an RSK inhibitor (SL0101), ABCB1 inhibitor (zosuquidar), or HIF-1α inhibitor." (PMID 33335181, 2020). "Upregulation of ABCB1, also known as p-glycoprotein, mediates resistance to THZ1 in neuroblastoma and lung cancer and resistance to both THZ1 and ICEC0942 in breast cancer cell lines." (PMID 32385714, 2020). "Recent studies have identified promoter translocations as common drivers of high ABCB1 expression in recurrent, chemotherapy-treated high-grade serous ovarian cancer (HGSC) and breast cancer." (PMID 33167906, 2020). "The overexpression of the transporters, such as ABCB1, known as P-glycoprotein, P-gp, ABCG2, known as breast cancer resistant protein, BCRP, and ABCC1, known as multidrug resistance-associated protein 1, MRP1, contributes to MDR." (PMID 32365495, 2020). "Here, we sought to determine the frequency and circumstances in which ABCB1 fusions arise in a large cohort of recurrent HGSC and a smaller series of breast cancer patients." (PMID 30894541, 2019). "Through down-regulating ABCB1, Apigenin (2, 8 μM) significantly enhances the efficacy of doxorubicin (Dox, an ABCB1 substrates) in its resistant MES-SA/Dx5 cells and breast cancer cells (MCF7/ADR)." (PMID 31245292, 2019). "This was accompanied by an increase in breast cancer stemness (SOX2, OCT4, and NANOG levels) and significant increase in the levels of key drug transporters (ABCG2, ABCB1, and ABCC1)." (PMID 31867270, 2019). "Our finding of frequent transcriptional fusions involving ABCB1 in recurrent HGSC and breast cancer has important implications for chemotherapy choice in disease relapse and the clinical development of targeted agents." (PMID 30894541, 2019). "In breast cancer, overexpression of HAS2 was reported to stimulate ABCB1 expression through the PI3K pathway, increasing resistance to doxorubicin." (PMID 31443261, 2019). "ABCB1, ABCB5, ABCB8, ABCC1, ABCC2, ABCC3, and ABCG2 were considered to confer resistance to doxorubicin on the breast cancer cells." (PMID 30202239, 2018). "This exploratory study aimed to investigate the interplay between preoperative statin use, ABCB1 genotype, and tumor-specific expression of the statin target 3-hydroxy-3-methylglutaryl-coenzyme A reductase (HMGCR) in breast cancer." (PMID 30370250, 2018). "Preoperative statin use, ABCB1 C3435T genotype, and HMGCR expression in relation to outcome were analyzed in 985 primary breast cancer patients from a population-based prospective cohort in Sweden from 2002 to 2012." (PMID 30370250, 2018). "Previous studies for breast cancer, acute leukemia and SCLC patients reported the correlations between ABCB1 expression and clinical response." (PMID 29765522, 2018). "ABCB1 3435TT and ABCG2 421CC genotypes were significantly correlated with longer PFS of the breast cancer patients." (PMID 29340035, 2017).
breast carcinoma (continued). "In this study, we examined the genotype frequencies of ABCB1 C3435T and ABCG2 C421A distribution in Chinese female breast cancer patients and healthy controls." (PMID 29340035, 2017). "Taken together, these data suggest that CUL4A is a critical component in chemoresistance, and H19, CUL4A, ABCB1 and ABCC4 work coordinately to display the action on modulation of multidrug resistance in breast cancer cells." (PMID 29190892, 2017). "In breast cancer, hypoxia inducible factor (HIF1α) induction can enrich the breast cancer stem cell population via interleukin 6 (IL6) and IL8 activation of ABCB1." (PMID 29117122, 2017). "We also detected ABCB1 C3435T and ABCG2 C421A genotypes in the cancerous and normal tissues from breast cancer patients." (PMID 29340035, 2017). "In the present study, we demonstrated that the expression of two ABC transporters, ABCB1 and ABCC11, which belong to different ABC transporter subfamilies, was increased in eribulin-resistant breast cancer cell lines." (PMID 27588398, 2016). "Our three bisulfite PSQ methods were applied to determine the promoter methylation levels of ABCB1, ABCC1 and ABCG2 in biopsy samples from 16 breast cancer patients." (PMID 27689338, 2016). "In the present study, we determined the promoter methylation patterns of ABCB1, ABCC1 and ABCG2 in human cancer cell lines, MDR cell models and tumor, tumor-adjacent and tumor-distant tissues from breast cancer patients." (PMID 27689338, 2016). "Hypomethylation of the ABCB1 promoter has been detected e.g. in MDR sublines of the human T-cell leukemia cell line CCRF-CEM and the breast cancer cell line MCF-7, obtained by selecting the parental cells for resistance to doxorubicin." (PMID 27689338, 2016). "Based on this result, we examined the expression of ABCB1 and ABCC11 in seven breast cancer cell lines and their eribulin-resistant cells by real-time RT-PCR and western blotting." (PMID 27588398, 2016). "Taken together, the Wnt5A signaling pathway was shown to contribute to regulating the drug-resistance protein ABCB1 and β-catenin-related genes in antagonizing the toxic effects of doxorubicin in the MDR cell lines and in clinical breast cancer samples." (PMID 25401518, 2014). "RASSF1A, ABCB1 and GSTP1 showed significantly higher quantitative methylation levels in late stage compared to the early stage breast carcinoma." (PMID 24093668, 2013). "In the present study, five genes, ABCB1, FOXC1, GSTP1, PPP2R2B and RASSF1A were hypermethylated already in early stage breast cancer (stage I and II)." (PMID 24093668, 2013). "Taxanes, drugs frequently used to treat breast cancer, are substrates for the ATP-binding cassette (ABC) transporter ABCB1." (PMID 20628376, 2010). "The upregulation of ATP citrate lyase (ACLY) increases the expression of the resistant proteins such as ABCB1/ABCG2, making breast cancer cells resistant to docetaxel, thereby suggesting ACLY as a potential predictive biomarker of tumor recurrence in breast cancer." (PMID 40843360, 2025). "Studies have shown that in PTX-resistant breast cancer cells, multiple ABC family proteins may be highly expressed simultaneously; further, simply inhibiting ABCB1 is insufficient to restore the sensitivity of cancer cells to the drug." (PMID 41304944, 2025). "By downregulating key efflux transporters like P-glycoprotein (ABCB1) and BCRP (ABCG2) and modifying chromatin accessibility, HDACis may enhance intracellular drug retention and re-sensitize resistant breast cancer cells to conventional chemotherapeutics." (PMID 40649736, 2025). "In addition, a bioinformatics analysis of TCGA breast cancer BRCA database showed a strong positive correlation between JUN and ABCB1, confirming our results that c-Jun potentiates the MDR1 expression in BC cells." (PMID 39470848, 2025).
breast carcinoma (continued). "ABCB1, the first identified ABC transporter, is well-known for its role in drug resistance, and subsequent discoveries revealed ABCC1 and ABCG2 as contributors to multidrug resistance in lung and breast cancer cells, respectively." (PMID 38397468, 2024). "Previously, we tested acetylated and deacetylated pairs of androstano-arylpyrimidines and showed that androstano-arylpyrimidine 17-acetates exhibited a remarkable potential to inhibit ABCB1 activity and sensitize multidrug-resistant MCF-7/KCR breast cancer cells to Doxorubicin-induced cell death." (PMID 36839907, 2023). "Other studies have shown that upon treatment of estrogen, multidrug-resistant ER-α-positive breast cancer cells downregulate P-gp but not ABCB1 RNA, suggesting a post-transcriptional mechanism of regulation." (PMID 37686513, 2023). "The second member of subfamily G, ABCG2, was originally cloned from a doxorubicin-resistant breast cancer cell line where resistance independent of ABCB1 was strategically sought out by selecting for drug resistance in the presence of a ABCB1 inhibitor." (PMID 37438132, 2023). "Thus, in the final experimental set, we monitored the effect of talazoparib on the expressions of ABCB1, ABCC1, and ABCG2 in breast cancer MCF-7 cells." (PMID 36430819, 2022). "ABCB1 is expressed in nonmalignant tissues (including the intestine and the blood–brain barrier) and malignant tissues, e.g., breast cancer and ovarian cancer tissues." (PMID 35627114, 2022). "In our qRT-PCR experiments, talazoparib did not cause significant transcriptional changes in ABCB1, ABCC1, and ABCG2 genes in the MCF-7 breast cancer cells." (PMID 36430819, 2022). "The promoter of ABCB1 is composed of several β-catenin/TCF4/LEF1-binding sites, which implies regulation of ABCB1 through the canonical Wnt/β-catenin pathway in colorectal and breast cancers." (PMID 36429127, 2022). "In addition, treatment with berberine downregulates the expression of ABC transporters, including ABCB1 and ABCC1 (also known as multidrug resistance protein 1 (MRP1)), thereby improving anti-growth effects of doxorubicin on breast cancer in vivo." (PMID 34575983, 2021). "Indeed, ABCB1 chromosomal rearrangements driving MDR have also been detected in ALL (acute lymphocytic leukemia) and breast cancer." (PMID 34830797, 2021). "Reduced expression of DNAJC15/MCJ is also correlated with increased drug resistance, as well as increased levels of c-JUN protein and its downstream target ATP binding cassette subfamily B member 1 (ABCB1)/multiple drug resistance 1 (MDR1), in ovarian and breast cancers." (PMID 34948322, 2021). "The results suggested that the STAT5a/ABCB1 pathway was at least one, if not the main, mechanism by which pimozide functions in drug-resistant breast cancer." (PMID 34336684, 2021). "Interestingly, the growth of tumour xenografts formed by ABCB1/MDR1-overexpressed MDR uterine sarcoma and breast cancer cell lines, knocked down for MET with shRNA, was reduced compared to tumours formed by control shRNA transfected cells." (PMID 33526881, 2021). "Expression of ABCB1, ABCC2, ABCG2, SLC22A16, and SLCO1A2 was significantly higher in normal breast tissue compared to tumorous tissue, while SLC22A1 and the tumor marker ESR1 showed a significantly higher expression in breast cancer tissue." (PMID 35008681, 2021). "Unfortunately, in clinical studies, the administration of these ABCB1 inhibitors, along with anticancer drugs, showed poor results, with no benefits on the OS and DFS in patients bearing different types of cancers, including breast cancer." (PMID 33801148, 2021). "This study describes possible mechanisms, that might contribute to upregulation of ABCB1 and synergistically boost the acquisition of doxorubicin (DOX) resistance in breast cancer MX-1 cell line." (PMID 33753859, 2021).